PARP1 (poly(ADP-ribose) polymerase 1)
Diseases named in the same sentence as PARP1 in open-access papers (continued):
Sharing a sentence is not in itself a finding about the gene and the disease.
tumor (continued). "Taken together, these results suggest that inhibition of AKT may modulate the activity or the expression of PARP1 in the tumor cells." (PMID 35419627, 2022). "In addition to clinical studies, a number of in vitro studies have shown that knockdown of PARP1 can inhibit the proliferation of tumor cells and reverse the platinum resistance." (PMID 35875162, 2022). "It was suggested that the anti-tumor effect of PARP-1 inhibitors could be further enhanced by combination use with autophagy inhibitors." (PMID 36353483, 2022). "We then found that PARP1 was gained or amplified across all tumor groups." (PMID 36344544, 2022). "HRR activity in tumor cells is a key factor for predicting whether treatment with a PARP1 inhibitor will be successful." (PMID 35643812, 2022). "Interestingly, single and double PARP-1 and PARP-2 deficiency play opposite roles in the tumor microenvironment." (PMID 35906622, 2022). "Indeed, the combination of c-Met and PARP1 inhibitors reduced tumor growth compared to either inhibitor alone." (PMID 35955544, 2022). "In summary, the toxicity profile of [211At]PTT was driven by PARP1 expression in normal tissues and was predictable, however; we observed a differential sensitivity between normal and tumor tissue that likely afforded a therapeutic window for [211At]PTT treatment." (PMID 36396952, 2022). "In particular, we show the suppression of tumour growth treated with boronsome with neutron irradiation and therapeutic outcomes are further improved by encapsulation of chemotherapy drugs, especially with PARP1 inhibitors." (PMID 35440126, 2022). "This suggested that PARP1 protein level in the tumor cells could be a potential marker to predict the combo effect, although more studies need to be carried out to further confirm this finding." (PMID 35419627, 2022). "The cytotoxicity based on this mechanism requires PARP-1 expression, since its silencing abolishes both PARPi trapping efficiency and cell killing effects, whereas PARP-2 (whose expression is much lower than PARP-1) has minimal influence on tumor sensitivity to PARPi." (PMID 36428727, 2022). "The enhanced expression of PARP1 in stroma cells may change the tumor microenvironment, which may explain the variation in the efficacy of PARP1 inhibitors in clinical application." (PMID 35875162, 2022). "Previous reports demonstrated higher PARP1 trapping ability and greater tumor exposure for Niraparib than other PARPis, which may account for Niraparib’s better antitumor effects." (PMID 36324587, 2022). "Although there is debate as to whether PARP1 is involved in the BER pathway, PARP1 inhibitors are significantly effective in tumor therapy." (PMID 36497058, 2022). "The encouraging tumour: muscle ratio of 1.3 indicates a tumour targeted PARP1 mediated uptake." (PMID 36104637, 2022). "PARP1 and PARP2 transcript levels were significantly higher in Tumor than Peri-Tumor and control tissues with PARG transcripts higher in all except NASH-associated Tumor tissues." (PMID 35804458, 2022). "The anti-tumor activities of PARP-1 inhibitors are regulated by both inhibition activities and allosteric mechanisms of PARP-1, and may also be involved in an autophagy-mediated process." (PMID 36353483, 2022). "Therefore, in addition to improving the anti-tumour activity of these benzodiazepine PARP-1 inhibitors, compound H52 would be selected to develop its potential use in neurodegenerative diseases." (PMID 35317687, 2022). "Similarly, the PARPi induced an increase in cell size in iNOS mRNA and, finally, the ability to kill tumor cells ex vivo in PARP1- or PARP2-null macrophages." (PMID 36223740, 2022). "Therefore, the purpose of inducing tumor cell apoptosis can be achieved by inhibiting the activity of PARP-1." (PMID 35963853, 2022). "In the present study, PARP1 expression in stroma cells of EOC may activate non-tumor cell repair to alter the tumor microenvironment, thereby enhancing the immune killing effect on tumor cells." (PMID 35875162, 2022).
tumor (continued). "Similarly, a microarray of FFPE tissues from 133 tumor samples revealed that patients with high PARP1 levels had lower PFS and OS." (PMID 35875162, 2022). "These things considered, these patients may benefit from the use of different PARP-1 inhibitors in order to limit tumor progression and therapy resistance." (PMID 35453444, 2022). "Recently, PBRM1-defecient tumor cells were shown to be sensitized to PARP1 inhibitor." (PMID 35719970, 2022). "Depending on the context, PARP1 has been reported to act as an oncogene or tumour suppressor." (PMID 36078035, 2022). "Thus, in addition to inflicting replication‐associated DNA damage and suppressing PARP1/2‐dependent DNA repair, PARPis act by enhancing the immunogenicity of BRCA1/2‐deficient tumours, thereby facilitating their elimination by the immune system." (PMID 35107878, 2022). "Depending on various conditions, PARP1 can be either tumor-suppressive or tumor-stimulatory." (PMID 35562364, 2022). "Many tumor cells express elevated levels of PARP1 and PARG, such as GSCs as we describe herein." (PMID 34806016, 2021). "Moreover, here, we determined PARG, a glycohydrolase involved in DNA-damage repair, and PARP-1 expression to better understand tumor cells going toward apoptosis after drug treatments." (PMID 34356835, 2021). "PARP1 expression was unchanged in the control, oral mucosal epithelial cells upon 5-FU treatment, confirming that upregulation of PARP1 reflects an acquired, post-treatment mechanism in some tumor cells." (PMID 35071239, 2021). "Another promising tumour-related biomarker is poly(ADP-ribose) polymerase-1 (PARP-1)." (PMID 34436048, 2021). "PARP1 inhibition in Trop2-driven NEPC significantly reduces NE function, tumor growth, and metastatic colonization in vivo, suggesting that PARP1 inhibitors may be a promising therapeutic strategy for metastatic PC expressing high levels of Trop2." (PMID 33921329, 2021). "High PARP1 immunoreactivity in the lymph node-negative group of patients was significantly associated with higher Breslow tumor thickness, presence of ulceration, and a higher mitotic index (p = 0.0016, p = 0.023, and p < 0.001, respectively)." (PMID 33572647, 2021). "Overexpression of DNA repair proteins such as PARP1, checkpoint kinase 1 (Chk1), and enhancer of zeste two polycomb repressive complex two subunit (EZH2) are independent of DNA-level mutations, but significantly contribute to tumor growth." (PMID 34531756, 2021). "We can speculate that decreased expression of DNA repair genes, like PARP1, reinforces and sustains DNA damage and its tumor suppressive signaling which in turn prevents damaged cells to resume their proliferation and/or induce cell death." (PMID 33594040, 2021). "Importantly, TRAF3IP2-AS1 regulated the expression of two tumor-related specific genes, PARP1 and PTEN." (PMID 33741027, 2021). "However, tumor cells can develop resistance to PARP1 inhibition, and further studies are needed to understand this mechanism." (PMID 33384409, 2021). "How PARP1 expression changes when neoplastic cells are in contact with each other (e.g., in 2D or 3D cell culture models or in vivo tumors) and how adhesion factors in the tumor stroma affect PARP1 expression are largely unexplored." (PMID 33922595, 2021). "The binding of PARP-1 can consistently demonstrate transcriptional regulation, positively or negatively, through several mechanisms, and appear differently according to the demands of the tumor microenvironment (mostly favorable directions for survival)." (PMID 33805293, 2021). "Similar results for an increased expression of PARP1 in tumor cells had already been published." (PMID 34073147, 2021).
tumor (continued). "PI3K/AKT/mTOR inhibitors sensitize tumor cells to PARP1 inhibitors and to radiotherapy." (PMID 34337349, 2021). "However, we have previously demonstrated that PARP1 mRNA is increased in pre-treatment OAC tumour samples from patients who exhibited subsequent poor pathological response to CRT, implicating a potential role for PARP1 in the resistance of OAC to CRT." (PMID 34440228, 2021). "PARP1 inhibitors are already in clinical use to suppress various tumours." (PMID 33541355, 2021). "Interestingly, inhibition of PARP-1 activity compromises base excision repair and promotes synthetic lethality in tumor cells with homologous recombination (HR) defects." (PMID 35111687, 2021). "Similarly, in a model of human skin cancer and chronic myelogenous leukemia, it was shown that PARP1 positively regulates the activity of activator protein-1 and hypoxia inducible factor 1 alpha, thereby promoting tumor cell survival and tumor growth." (PMID 34686201, 2021). "Because of PARP1’s relevance in many tumor types, this is a highly active field of research." (PMID 33589610, 2021). "Impressively, PARP1 mutation was markedly associated with higher levels of immune infiltrates, such as CD8+ T cells, in several tumor types, suggesting that tumors with PARP1 mutations could be classified as active immune subtypes." (PMID 34531868, 2021). "By adding PARP1-i and applying a (modest) RT/cDDP dose reduction in those treatment regimens, we might achieve an improvement in the tumor control combined with a reduction of toxicity and occurrence of severe side effects." (PMID 33926008, 2021). "PARP1 also participates in hormone-dependent tumor pathogenesis." (PMID 33572647, 2021). "Moreover, PARP1 knockdown or olaparib was shown to result in significant inhibition of tumor growth using xenografts of human MM cells." (PMID 33525741, 2021). "However, although additional proteins have been reported to interact with PARP1, little is known about their relevance for the anti-tumor activity or the emergence of resistance to PARP1i in the context of HGSOC." (PMID 34686201, 2021). "Since CD38 could consume NAD+, NAD+ would be elevated by CD38 knock-out and then might stimulate SIRT1 and PARP1 to induce T cell differentiation into Th1 subsets for enhancing the anti-tumor effects." (PMID 34226519, 2021). "Thus, PARP1 upregulation during oral tumor recurrence correlated with increased PARylation, decreased DNA damage accumulation, and acquired drug resistance." (PMID 35071239, 2021). "Depending on the degree of its activation, PARP1 can act as a tumor promoter or suppressor." (PMID 33384409, 2021). "Possibly PARP-1 inhibition can suppress damaged DNA repair and improve tumor killing." (PMID 33572586, 2021). "PARP-1 participates in several processes responsible for the resistance of tumor cells to therapy." (PMID 34768872, 2021). "ERN, LP-ERN and Tf-LP-ERN enhanced the expression levels of Bax, Bad, and PUMA, promoted the cleaved caspase-3, cleaved-9 and PARP-1, and reduced the expression level of Bcl-2, which induced apoptosis and thus to inhibited tumor growth in xenotransplanted BALB/c nude mice." (PMID 34513705, 2021). "Additionally, the protein expression from extracted tumor also demonstrated the induction of cleaved caspase-3, 8, -9 and PARP-1 by imipramine." (PMID 34765548, 2021). "A recent study reported that PARP1 could ADP-ribosylate the regulatory T-cell (Treg)-specific transcription factor FOXP3, that negatively regulates the function of Treg cells, and PARP1 silencing can enhance PDL1 expression in tumor cells." (PMID 34531868, 2021). "PARP1 inhibitors can enhance the efficacy of radiotherapy, alkylating agents and platinum-based chemotherapy by inhibiting DNA damage repair and promoting apoptosis of tumor cells." (PMID 34497808, 2021). "Several tumor-driving growth factors are regulated by PARP1." (PMID 33922595, 2021).
tumor (continued). "Therefore, inhibitors of PARP1 or POLQ can block the Alt-EJ pathway and kill HR-deficient tumor cells." (PMID 34066020, 2021). "The most recently published multicenter, open-label, phase 1a/b trial (NCT02660034) from Australia, investigated the safety and anti-tumor effects of pamiparib, an oral PARP1/2 inhibitor, combined with tislelizumab, a humanized anti-PD-1 monoclonal antibody, in patients with advanced solid tumors." (PMID 34026622, 2021). "PARP1 was now considered to be a central regulatory hub of cell survival and cell death as well as a key component of a number of transcription factors involved in tumor development and inflammation." (PMID 34773055, 2021). "This positive correlation between the expression levels of HuR and PARP1 in tumor cells may indicate the significance of PARP1 in HuR functions in another physiopathological context." (PMID 32789690, 2021). "However, during disease progression, PARP1 activates NFκB, which promotes the secretion of pro-inflammatory cytokines (IL-1β, IL-6), allowing tumour-promoting inflammation." (PMID 34440228, 2021). "Furthermore, owing to this, ablation of Parp1 transcriptional activity was shown to counteract the effects of E2f1-induced hyper-replication on embryonic development and tumour growth." (PMID 33050515, 2020). "Cleavage of PARP1 was more prominent in tumor extracts of mice receiving L. casei compared to control mice, as evidenced by a decrease in the levels of the full-length protein at 116kDa and subsequent increase in the intensity of the cleaved fragment at 89 kDa." (PMID 32033490, 2020). "In addition to these commercially available PARP-1 drugs, numerous PARP-1 inhibitors have also entered different phases of clinical research, targeting multiple types of tumor either collectively or as single agents." (PMID 32509471, 2020). "Genome-wide and high-density CRISPR-Cas9 screening in PARPi resistant tumor cells identified that PARP1 intramolecular interactions might influence PARPi-mediated cytotoxicity." (PMID 33324554, 2020). "In parallel with mRNA assays, Western blot results showed that FGFR1 and PARP1 protein expression levels were 1.55- and 1.84-fold higher, respectively, in poorly differentiated FGFRi-resistant primary tumor PANC-1 cells than FGFRi-sensitive metastatic SUIT-2 cells." (PMID 32276472, 2020). "The Kaplan–Meier shows a significant retardation of Parp1−/− tumours compared to the control group." (PMID 33050515, 2020). "for deleterious ERCC4 variants, the effectiveness of cisplatin is expected for disrupting mutations; PARP inhibitors are selectively toxic to tumours with RAD51C mutations, and tumours with ATM mutations had a positive response to cisplatin, and inhibitors of PARP1, ATR and DNA-PKc." (PMID 32756499, 2020). "PARP1 expression or protein level is relevant for tumor prognosis." (PMID 32455851, 2020). "MacroH2A acts as a tumour suppressor and is a significant player in the maintenance of the heterochromatic structure as well as in the inactivation of the X chromosome, during which macroH2A inhibits the enzymatic activity of PARP1." (PMID 31940791, 2020). "Together, these in vitro results indicated that PARP1 inhibited PD-L1 transcription and expression, and could promote the activity of tumor-infiltrating lymphocytes." (PMID 32245950, 2020). "It has been suggested that an abundance of phosphorylated PARP1 may predict tumor resistance and that the combination of c-Met and PARP inhibitors may benefit patients whose tumors demonstrate high levels of c-Met expression." (PMID 32180937, 2020). "Therefore, our goal was to genotype PARP1 SNPs in paired NSCLC tumor and normal tissues in a population of European ancestry, construct haplotypes and test for association with NSCLC subtypes and PARP1 expression at the transcript and protein levels." (PMID 33284833, 2020).
tumor (continued). "In vivo tumor characterization facilitated by PARP1 imaging could become a valuable instrument for personalized therapy in patients, which is the need of the hour." (PMID 32640708, 2020). "Since it has similar pharmacokinetic and pharmacodynamic properties as its parental drug, apart from its use as a PARP1 targeting tracer, it can also provide insights into the systemic behavior of olaparib with regard to tumor accumulation and therapeutic dosage." (PMID 32640708, 2020). "Interestingly, the potential of PARP-1 inhibitor in non-tumor diseases has been put forward by some researchers and clinical physicians, especially in the scope of CNS diseases." (PMID 32317937, 2020). "In addition, as angiogenesis is a fundamental characteristic of carcinogenesis, it has been found that PARP1 regulates tumor-related gene expression involved in angiogenesis in skin carcinogenesis, such as HIF-1 α, Pecam-1, and OPN." (PMID 33665167, 2020). "Also, TMZ combined with PARP1 inhibitor olaparib significantly inhibited tumor growth in mice in the HG7R NC group, which was consistent with the enhanced TMZ sensitivity induced by ATRX knockout in the HG7R KO group." (PMID 32194873, 2020). "In contrast, tumour development was less frequent in Parp1−/−Rb+/− mice (77.8%; 14/18)." (PMID 33050515, 2020). "We explored whether this PARP1 disruption (PARP1m) could significantly lower the chemotherapeutic dose necessary to achieve therapeutic efficacy in both a 2D and 3D tumor‐on‐a‐chip model." (PMID 31989039, 2020). "Moreover, patients pre-treated with platinum-based chemotherapy show elevated PARP1 levels in the tumor microenvironment." (PMID 32640708, 2020). "BER as one of the DNA repair mechanisms, PARP1 may be one of the major genes involved in tumor cell metastasis." (PMID 33184404, 2020). "Indeed, increased expression of PARP1 has been found to be a strategy for tumor cells treated by radiation and chemotherapeutic drugs to avoid apoptosis induced by DNA damage, which results in apoptosis resistance." (PMID 33665167, 2020). "Moreover, downregulation of miR-362-5p promoted the protein levels of QKI, MacroH2A1.1, PARP-1, p27 in tumor tissues, while reduced the protein levels of Cyclin D, MacroH2A1.2, c-Fos, and E2F1." (PMID 32194406, 2020). "Notably, PARP1 contributes to epigenetic regulation and controls the transcription of genes that are crucial for tumor survival and progression due to their involvement in proliferation, DNA repair, metabolism, and many other processes." (PMID 32900001, 2020). "Our mechanistic studies further revealed that the KLF4 transcriptional function is regulated by several types of posttranslational modifications, including PARP1 in response to DNA damage signal, which determines tumor cell survival in the presence of genotoxic stress." (PMID 33231937, 2020). "Finally, Akt activation inhibits PARP1-mediated apoptosis and promotes survival of tumor cells during extravasation and tissue invasion." (PMID 31965270, 2020). "They observed that up to 60% of tumours showed weak PARP1 protein expression." (PMID 32594311, 2020). "Upon MMS‐induced DNA damage, we were unable to detect PARylated HMGA2 in Parp1 knockout MEFs but readily showed HMGA2 PARylation in wild‐type MEF cells demonstrating that PARP1 was responsible for DNA damage‐induced PARylation of HMGA2 in our tumor cell models." (PMID 30289618, 2019). "Chemical inhibition of PARP1 synergized with the G-quadruplex ligand RHPS4 in HT29 xenografts could further inhibit tumor cell growth by preventing the repair of uncapped telomere ends." (PMID 30551210, 2019).